TNIP2 (TNFAIP3 interacting protein 2)
Description:
Inhibits NF-kappa-B activation by blocking the interaction of RIPK1 with its downstream effector NEMO/IKBKG. Forms a ternary complex with NFKB1 and MAP3K8 but appears to function upstream of MAP3K8 in the TLR4 signaling pathway that regulates MAP3K8 activation. Involved in activation of the MEK/ERK signaling pathway during innate immune response; this function seems to be stimulus- and cell type specific. Required for stability of MAP3K8. Involved in regulation of apoptosis in endothelial cells; promotes TEK agonist-stimulated endothelial survival. May act as transcriptional coactivator when translocated to the nucleus. Enhances CHUK-mediated NF-kappa-B activation involving NF-kappa-B p50-p65 and p50-c-Rel complexes.
Synonyms: ABIN-2; ABIN2; FLIP1; MGC4289; KLIP
Tractability: PROTAC: UniProt records ubiquitination sites on it; ubiquitination databases record sites on it; its protein half-life has been measured.
Gene: Protein-coding gene on chromosome 4 (2,741,648 to 2,756,367, reverse strand). Ensembl gene ENSG00000168884.
Subcellular location: Cytoplasm; Nucleus
Subcellular location (Human Protein Atlas): Nucleoplasm; Cytosol
Pathways (Reactome):
Immune System: MAP3K8 (TPL2)-dependent MAPK1/3 activation
Metabolism of proteins: Ovarian tumor domain proteases
Gene Ontology:
Molecular function: polyubiquitin modification-dependent protein binding; protein binding; protein kinase binding; K63-linked polyubiquitin modification-dependent protein binding
Biological process: negative regulation of endothelial cell apoptotic process; positive regulation of canonical NF-kappaB signal transduction; positive regulation of transcription by RNA polymerase II; CD40 signaling pathway; cellular response to lipopolysaccharide; interleukin-1-mediated signaling pathway; positive regulation of B cell activation; positive regulation of macrophage activation; protein stabilization; regulation of transcription by RNA polymerase II; toll-like receptor 2 signaling pathway; toll-like receptor 3 signaling pathway; toll-like receptor 9 signaling pathway; regulation of canonical NF-kappaB signal transduction
Cellular component: cytoplasm; cytosol; nucleoplasm; nucleus
Genetic constraint (gnomAD): Loss-of-function variants: 30 observed, 34.65 expected, observed/expected ratio (o/e) 0.87, 90% interval 0.65 to 1.17. The upper end of that interval is the gene's LOEUF score, 1.17, which puts it in group 5 of 6, group 1 being the genes least tolerant of losing a copy. Missense variants: 595 observed, 524.74 expected, observed/expected ratio (o/e) 1.13, 90% interval 1.06 to 1.21. Synonymous variants: 259 observed, 218.89 expected, observed/expected ratio (o/e) 1.18, 90% interval 1.07 to 1.31.
Homologues: Orthologues: macaque TNIP2 (93% identical), pig TNIP2 (81% identical), chimpanzee TNIP2 (80% identical), mouse Tnip2 (79% identical), rat Tnip2 (78% identical), dog TNIP2 (78% identical), rabbit TNIP2 (52% identical), tropical clawed frog tnip2 (43% identical), zebrafish tnip2 (32% identical). Paralogues in human: TNIP1 (19% identical), TNIP3 (10% identical).
Diseases named in the same sentence as TNIP2 in open-access papers:
TNIP2 is named in the same sentence as 26 diseases in open-access papers, as found by Europe PMC text mining. Sharing a sentence is not in itself a finding about the gene and the disease. The quoted sentences say what the papers report.
breast carcinoma (3 papers, 2019 to 2024). "In the I-Kappa B kinase signaling pathway, our method found genes 4792 (NFKBIA), 23,476 (BRD4), and 79,155 (TNIP2) to be significantly associated with breast cancer survival." (PMID 31874600, 2019). "In breast cancer, miR-423 activates the NF-κB pathway by regulating TNIP2." (PMID 39337604, 2024).
lupus nephritis (3 papers, 2020 to 2023). Glomerulonephritis in the context of systemic lupus erythematosus. "miR-423-5p modulates the activation of NF-kB by targeting TNIP2 and contributes to the pathogenesis of lupus nephritis." (PMID 34207555, 2021). "For example, miR-423-5p is involved in lupus nephritis via regulating the activation of NF-κB and targeting TNIP2." (PMID 32454787, 2020). "Furthermore, previous work showed that TNIP2 was involved in Lupus nephriti development." (PMID 37904691, 2023).
endometritis (2 papers, 2023 to 2024). An acute or chronic, usually bacterial infectious process affecting the endometrium. "The findings revealed that TNIP2 alleviated endometritis by inhibiting the NF‐kB pathway, suggesting a potential therapeutic target for endometritis." (PMID 37904691, 2023). "TNIP2 alleviated endometritis by inhibiting the NF‐κB pathway, suggesting a potential therapeutic target for endometritis." (PMID 37904691, 2023). "In our study, we found that TNIP2 overexpression prevented LPS‐induced endometritis in vitro, evidenced by reduced cell apoptosis, inflammatory response, and inhibited oxidative stress in LPS‐induced hEECs." (PMID 37904691, 2023). "The present study explored the role of TNFAIP3 interacting protein 2 (TNIP2) in endometritis that stimulated by lipopolysaccharide (LPS) at human endometrial epithelial cells (hEECs)." (PMID 37904691, 2023). "This study aimed to explore the role of TNFAIP3 interacting protein 2 (TNIP2) in endometritis through human endometrial epithelial cells (hEECs) stimulated by lipopolysaccharide (LPS)." (PMID 37904691, 2023). "In our research, we found that TNIP2 overexpression notably inhibited the LPS‐induced endometritis via the NF‐κB pathway." (PMID 37904691, 2023). "RT‐qPCR and western blot analysis were performed to determine TNIP2 expression in LPS‐induced endometritis cell model." (PMID 37904691, 2023). "TNIP2 was downregulated in the LPS‐induced endometritis cell model." (PMID 37904691, 2023). "Moreover, the results hinted that NF‐κB was involved in the effects of TNIP2 on the LPS‐induced endometritis cell model." (PMID 37904691, 2023). "In this study, effects of TNIP2 on LPS‐induced endometritis were investigated." (PMID 37904691, 2023). "Therefore, we conducted this study to explore the effect of TNIP2 on endometritis induced by LPS and to elucidate its mechanism of action." (PMID 37904691, 2023). "In conclusion, we described in detail that TNIP2 mitigates LPS‐induced endometritis in vitro." (PMID 37904691, 2023). "Nevertheless, whether TNIP2 mediated the endometritis through the NF‐κB pathway is still unknown." (PMID 37904691, 2023). "However, only a few studies have investigated the effects of TNIP2 on endometritis." (PMID 37904691, 2023). "Therefore, this study aimed to determine the effect of TNIP2 on endometritis." (PMID 37904691, 2023). "Therefore, our data suggest that TNIP2 may serve as a new target for treating endometritis." (PMID 37904691, 2023). "However, it remains unclear whether TNIP2 affects endometritis." (PMID 37904691, 2023). "Moreover, this study did not explore the role of TNIP2 in the animal model of endometritis." (PMID 37904691, 2023).
hepatocellular carcinoma (2 papers, 2019 to 2020). A malignant tumor that arises from hepatocytes. "The expression of miR‐1180 is significantly increased in hepatocellular carcinoma cells and tissues, which promotes cell proliferation of hepatocellular carcinoma by targeting TNFAIP3 interacting protein 2 (TNIP2)." (PMID 32961635, 2020). "MiR-1180 promotes hepatocellular carcinoma cell proliferation by down-regulating TNIP2 expression and induces apoptosis-resistance by activating NF-κB signaling pathway." (PMID 30936781, 2019).
lung carcinoma (2 papers, 2021 to 2022). "cg07094298 in the gene body of TNIP2 was previously identified as causal for lung cancer." (PMID 35546478, 2022).
pulmonary arterial hypertension (2 papers, 2021 to 2022). Pulmonary arterial hypertension (PAH) is a group of diseases characterized by mean pulmonary artery pressure >20 mmHg and elevated pulmonary arterial resistance leading to right heart failure. "It was reported that a missense variation in the TNIP2 gene was found in two patients with pulmonary arterial hypertension (PAH), indicating TNIP2 also has a role in BPD, as about 25% of infants with moderate to severe BPD would develop BPD-PAH." (PMID 35433535, 2022).
Sepsis (2 papers, 2023). Sepsis is defined as life-threatening organ dysfunction caused by a dysregulated host response to infection. "Furthermore, miR-15a-5p might be involved in the inflammatory cascade during sepsis, potentially via the activation of the NF-κB pathway and targeting TNIP2." (PMID 38140218, 2023). "In addition, in a mouse sepsis model, a miR-15a-5p inhibitor could reduce the activation of the NF-κB pathway by targeting TNIP2, significantly suppressing the secretion of inflammatory factors and the level of creatine and blood urea nitrogen, which could protect against sepsis." (PMID 37081490, 2023).
endometriosis (1 paper, 2019). The growth of functional endometrial tissue in anatomic sites outside the uterine body. "TNIP2 is a hub protein in the NF-κB network, and NF-kB has an important role in the pathophysiology of endometriosis." (PMID 31552087, 2019).
glioblastoma (1 paper, 2017). The most malignant astrocytic tumor (WHO grade IV). "To determine whether deregulation of negative regulators of NF-κB has a role in constitutive NF-κB activation in glioblastoma, we analyzed expressions of the NF-κB regulators NFKBIA, TNFAIP3, TNIP1 and TNIP2 in glioblastoma patients from The Cancer Genome Atlas (TCGA)." (PMID 28166199, 2017).
lung adenocarcinoma (1 paper, 2022). A carcinoma that arises from the lung and is characterized by the presence of malignant glandular epithelial cells. "A recent study reported TNIP2‐ALK fusion in lung adenocarcinoma." (PMID 35546478, 2022).
osteoarthritis (1 paper, 2023). A noninflammatory degenerative joint disease occurring chiefly in older persons, characterized by degeneration of the articular cartilage, hypertrophy of bone at the margins and changes in the synovial membrane. "LncRNA NAV2-AS5 alleviated chondrocyte inflammation via inhibition of miR-8082 and upregulation of TNFAIP3 interacting protein 2 (TNIP2) in osteoarthritis." (PMID 37779916, 2023).
pancreatic cancer (1 paper, 2019). "As an example, TNIP2 may be a TSG in pancreatic tumors, since it was shown that inhibition of MiR-1180, a short non coding mi-RNA over-expressed in pancreatic cancer targeting TNIP2, inhibited cell proliferation." (PMID 31568528, 2019).
cancer (6 papers, 2015 to 2025). A tumor composed of atypical neoplastic, often pleomorphic cells that invade other tissues. "The protein encoded by the TNIP2 gene is also considered an important inhibitor of the NF-κB pathway and is known to regulate tumor aggressiveness in various cancer types." (PMID 40446009, 2025). "And TNIP2 is less reported in cancer and is more like passenger mutation, so the mutation sharing here may be due to technical bias of sequencing or some accumulated alterations due to HBV infection." (PMID 35795211, 2022). "First, in terms of immune function, variations related to the nuclear factor kappa B (NF-κB) signaling pathway (NLRP12, TNIP2, IRAK4) and the autophagy process (TECPR1, ATG2A, SOGA1, TOM1) were identified in both carcinoma and sarcoma tumor groups." (PMID 40446009, 2025).
tumor (6 papers, 2015 to 2025). "As shown by the phylogenetic tree, 345 mutations occurred in either of tumor, while only TNIP2 was a shared early mutation." (PMID 35795211, 2022). "The results showed that OTUD7B, TNIP2 and BAD, which are closely correlated with cell survival and apoptosis progression in tumours, were three putative targets of miR-1180." (PMID 26928365, 2016).
TNIP2 also shares sentences with these, for which no sentence is quoted: lymphoma (2 papers); bronchopulmonary dysplasia (1); cardiovascular diseases (1); chronic lymphocytic leukemia (1); depression (1); infection (1); large cell lymphomas (1); melanoma (1); Obesity (1); pancreatic tumors (1); primary biliary cirrhosis (1); viral infection (1).